COL1A2 (collagen type I alpha 2 chain)
Diseases named in the same sentence as COL1A2 in open-access papers (continued):
Sharing a sentence is not in itself a finding about the gene and the disease.
tumor (continued). "In additions, clusters 4, 7 and 10 expressed a variety of collagen proteins including COL1A1, COL1A2, COL3A1, COL6A1 and COL6A3, which have been previously linked to abilities of proliferation, invasion, metastasis and drug resistance of tumor cells." (PMID 37644609, 2023). "For example, collagens, such as COL1A1, COL1A2, COL3A1, COL5A2, COL6A1, COL6A2, and COL6A3 are thought to mediate tumor progression and are associated with a poor prognosis in BCa." (PMID 37277784, 2023). "Col1a2 and Col3a1 are more expressed when Vascular smooth muscle cells contact Tumor III cells (VSMC+Tumor III)." (PMID 37815040, 2023). "Collagen such as COL1A1/COL1A2/COL3A1 can change the resistance of tumor cells by interacting with the ITGB1 integrin, as reported for other cancers." (PMID 36460803, 2023). "Next, we further investigated the correlation between COL1A2 expression and tumor immune cell infiltrates against tumor purity based on TIMER database." (PMID 37805556, 2023). "After performing survival analysis, hsa-miR-552-3p was selected as the most potential upstream tumor suppressive miRNA of COL1A2." (PMID 37805556, 2023). "Upon immunohistochemical (IHC) analysis of FFPE blocks however, COL1A2 showed better differential staining between tumor epithelia and tumor stroma." (PMID 37626157, 2023). "In summary, this present study showed that radiotherapy significantly upregulated the expression of COL1A1, COL3A1, and COL1A2 genes in BCa tumor tissues." (PMID 35274048, 2022). "An in vivo model of tumor recurrence was established using Col1a2;rtTATetO7-Prrx1Luc mice, and the effect of fibroblast-specific Prrx1 expression on tumor recurrence was evaluated." (PMID 35589735, 2022). "Subcellular location and immunofluorescence image of COL1A2 expression in human tumor cells were retrieved from the HPA." (PMID 36057263, 2022). "In this cluster, we identified 148 differentially expressed genes, including a significant downregulation of Col1a1 and Col1a2 in tumours grown in Atf4Δ/Δ mice." (PMID 35654839, 2022). "Three over-expressed, amplified, and mutated molecules were identified as tumor antigens, i.e., KDR, COL1A2, and SAMD9, and found to be associated with unfavorable prognosis." (PMID 34815785, 2021). "After adjusting the analysis by tumor purity, we found that the expression levels of COL1A2, COL1A1, COL3A1, ZNF469 and Periostin (POSTN) were significantly correlated with tumor purity in ESCA." (PMID 33543230, 2021). "TGF‐β1, tumour cell CM and Cocl2 notably increased the expression of Col1a2 and Acta2 of fibroblasts at RNA levels." (PMID 33943003, 2021). "To further determine the effect of HIF‐1α expression on the activation of fibroblasts, we examined the effects of TGF‐β1, tumour cell CM and Cocl2 on Acta2 and Col1a2, which are markers of CAFs." (PMID 33943003, 2021). "The genetic deletion of IKKβ in COL1A2 + CAFs in the similar CAC model unexpectedly accelerated tumor growth." (PMID 33614646, 2021). "COL1A2, COL3A1, COL5A1 encode the collagen family, whose members are the main components of the tumor-stromal environment and play an important role in behavior of cancer cells." (PMID 34795689, 2021). "TPL-mediated disruption of cell-specific SEs to downregulate gene expression (MYC, BRD4, RNA Pol II, COL1A2, etc.), as elucidated here, implies its therapeutic relevance in targeting both stromal and tumor compartments of PDAC." (PMID 33168807, 2020). "For example, the high expression of THBS2 and COL1A2 facilitated GC proliferation and invasion but inhibited tumor apoptosis through the PI3K-Akt signaling pathway." (PMID 33080572, 2020). "The data here demonstrated a survival advantage associated with high COL1A2 expression in patients with PDAC, but, importantly, this was not significant on multivariate analysis where other patients and tumor characteristics dominated the survival model." (PMID 27895310, 2017).
tumor (continued). "We used 5 different Cre strains to generate tumor study cohorts: Col1a2-Cre (Cre+n = 16, Cre-n = 6), Dermo1-Cre (Cre+n = 25, Cre-n = 18), P0-Cre (Cre+n = 20, Cre-n = 15), Prx1-Cre (Cre+n = 25, Cre-n = 24), and Sox9-Cre (Cre+n = 21, Cre-n = 15)." (PMID 27191748, 2017). "COL1A2 mRNA expression was related to tumor size and depth of invasion, and high COL1A2 mRNA expression was positively associated with poor overall survival time." (PMID 27894325, 2016). "Binding of secreted COL1A2 to integrins, such as integrin α2β1 on the surface of tumors, has also been shown to drive tumor cell migration via the activation of RhoC and PI3 kinase." (PMID 27152194, 2016). "Among five CpG loci whose methylation was significantly associated (Q<0.05) with lymph node status, four (two in COL1A2, and one each in LOX and P2RX7) were also associated with tumor size (Q<0.05)." (PMID 20686660, 2010). "Furthermore, the survival associations for COL1A2, PAWR and MED10 suggest potential tumor-suppressive roles, supporting their roles in tumor progression as they are upregulated in adenocarcinoma samples in our analysis." (PMID 40362431, 2025). "For instance, while COL1A2 suppresses fibrosarcoma cell migration, it paradoxically promotes chondrosarcoma cell motility, suggesting its functional divergence through interactions with distinct molecular partners across tumor microenvironments." (PMID 41561769, 2025). "In addition to carrying the Braf gene, chromosome 6 carries several genes that are highly expressed in the LNM and tumor populations (Aqp1, Col1a2, Cav1, Cav2, Ptn, RaRes2, Fkbp9, Actg2, Ybx3, Mgp, Sox5, Kcna1, and Ptms)." (PMID 40571713, 2025). "In this context, MSCMel were found to increase tumor collagen deposition and to modulate molecules primarily associated with collagen folding, such as COL1A2 and COL12A1, suggesting a potential link between these molecular changes and collagen-mediated tumor growth inhibition." (PMID 40083939, 2025). "In GC, COL1A2 has been identified as a potential biomarker for tumor progression and prognosis." (PMID 38913913, 2024). "Notably, COL1A1, COL1A2, and FAP were closely associated with CAF-mediated functions related to carcinogenesis and tumor metastasis." (PMID 39034310, 2024). "Our findings suggest that the oncogenic roles of COL1A2 in COAD may be partially attributed to tumor immune infiltration." (PMID 37805556, 2023). "Also, among the hub genes of the NAT, SN, and SNAT lists, COL1A2 (12%), KRAS (14%), and VCAN (9%) have a higher mutation rate in tumour samples, respectively." (PMID 37118990, 2023). "Also worth mentioning is that the expression of COL1A2 was positively correlated with common immunoinhibitors and immunostimulators, indicating that COL1A2 played complex immunological roles in the tumor microenvironment of COAD." (PMID 37805556, 2023). "We have successfully constructed a reverse mRNA prediction model based on LINC00638/hsa-miR-552-3p/COL1A2 ceRNA network as the upstream regulatory mechanism of COL1A2, which advances our understanding of the pathogenesis of this very common tumor and paves the way for further cancer therapeutics." (PMID 37805556, 2023). "Also, the cooperation pathways between COL1A2 expression and tumor-infiltrating immune cells require further clarification in the future." (PMID 37805556, 2023). "Our data revealed that CK19, COL11A1, and COL1A2 could be potential tumor biomarkers in plasmatic EVs, since results both at the level of expression as well as specificity and reproducibility are robust and promising." (PMID 36834987, 2023). "In particular, genes encoding collagen, including COL1A1, COL1A2, COL6A1, and COL6A3, are upregulated in tumor tissue and also highly expressed in late-stage cancer patients; they are predicted to interact with SDC1 and SDC4 in tumor cells to promote the pEMT phenotype of tumors." (PMID 38002057, 2023). "This indicates the potential role of COL1A2 expression in regulating tumor immune abundance." (PMID 37805556, 2023).
tumor (continued). "Furthermore, MS-proteomic analysis of the tumours detected Col1a1 and Col1a2 peptides containing 13C5-proline (datasheet ‘H/L ratio collagen peptides’)." (PMID 35760868, 2022). "Of these, only COL1A2 was elevated in the CM from the tumor-associated group 1, but not in the non-tumor-associated group 2, hiPSC-sensory neurons, as well as in mouse Nf1+/neo but not Nf1+/1809 DRG neurons (2.4–3.2-fold increase)." (PMID 35589737, 2022). "Notably, the vCAFs were substantially reduced in Atf4Δ/Δ mice, and Col1a1 and Col1a2 were significantly downregulated only in the vCAF subcluster in the small tumours in Atf4Δ/Δ mice." (PMID 35654839, 2022). "This indicates that expression changes of the TPX2/AURKB subnetwork likely reflect tumor intrinsic features while those of the COL1A2 subnetwork likely captures features of stromal cells in the tumor microenvironment impacted by alterations in tumor cell aurora kinase signaling." (PMID 35332150, 2022). "Additionally, COL1A2 was secreted by stromal fibroblasts, while tumor-associated fibroblasts stimulate the occurrence of COAD in part by inducing inflammation in the tumor microenvironment." (PMID 36057263, 2022). "The hyper-proliferative neoplastic cells may induce COL1A2 degradation to facilitate tumour invasion." (PMID 33889206, 2021). "Our in silico study reveals that an abundance of COL11A1 mRNA could induce the transcriptional upregulation of THBS2, COL10A1, COL5A2, and COL1A2 genes cooperatively, to promote the neoplasia." (PMID 33597969, 2021). "However, higher COL1A2 mRNA expression, tumor region, age stage, gender stage, and primary site progression were not correlated with overall survival." (PMID 35047627, 2021). "Our results show a significantly higher mRNA expression of MMP1, MMP9, POSTN, GREM1, FMOD, and COL1A2 in tumor biopsies compared to normal tissue, but the significant difference between responder and non-responder groups was only found for the expression of FMOD mRNA." (PMID 34283070, 2021). "Circulating bone formation (P1NP) and bone resorption (CTX) markers were not different between genotypes at 5 and 15 weeks and mRNA expression of the major collagens Col1a1, Col1a2 and Col3a1 appeared comparable in tumor-bearing bones at 5 weeks and in primary OS cells." (PMID 32686768, 2020). "Moreover, COL1A1 expression was unrelated to clinicopathological parameters, while COL1A2 expression was positively related to tumor size and depth of invasion." (PMID 27894325, 2016). "COL1A2, the most abundant protein in the human body, indeed increases the synthesis in colon malignancy and reveals a considerably higher expression in stage II tumours, suggesting that its activation is an early event in CRC tumorigenesis." (PMID 26993598, 2016). "Indeed, these rates were higher than methylation frequencies of other tumor suppressor loci such as p16 (52%), COL1A2 (48%), H-cadherin (43%) and E-cadherin (40%)." (PMID 25734919, 2015). "Interestingly, we also found significantly increased and coordinated up-regulation of COL1A1 and COL1A2 in the tumor tissue, both of which are important in blood vessel development." (PMID 24321518, 2013). "Genes such as COL1A2, VIM, and TGFB1/TGFB4, which are associated with tumor cell invasiveness and tissue remodeling, were not only expressed in infiltrative tumor cells but also broadly present in the surrounding peritumoral tissues influenced by the tumor milieu." (PMID 40725477, 2025). "To explore whether SpatialSNV is able to identify essential SNVs in tumorigenesis, we utilized transcriptomics data to divide the tumor section into the tumor (marked by EPCAM and other tumor-associated markers), tumor-adjacent margins (marked by VIM, COL1A2, PTPRC), and normal tissues." (PMID 40515555, 2025).
tumor (continued). "Additionally, collagen proteins (COL1A1, COL1A2, COL3A1, COL11A1) were linked to tumor progression and metastasis, while chaperonin-containing TCP1 (CCT) complex proteins and microtubule-associated proteins (TUBA1C, TUBB) were implicated in cytoskeletal organization and chemotherapy resistance." (PMID 40867231, 2025). "Thus, the model used is suitable for this study as we are interested in examining the interplay of Col1A2-Cre-fibroblasts with the tumor environment and, specifically, the role of the matricellular protein CCN1 in coordinating this process, including its potential role in ICI resistance." (PMID 38363129, 2024). "Furthermore, our present data suggested that tumor immune infiltration and tumor immune escape might be involved in COL1A2-medidated cancer development, providing clues for improving the immunotherapy efficacy of COAD by targeting COL1A2." (PMID 37805556, 2023). "Additionally, p28 co-administration with iRGD and 5-FU, or therapy with p28 and 5-FU, dramatically decreased the expression of the CoL1a1 and CoL1a2 genes in the tumor tissues when compared with the mice receiving solo therapy with p28 or 5-FU (P<0.05 and P<0.001, respectively)." (PMID 37396945, 2023). "Interestingly, col1A2 has been reported as a tumor suppressor gene that could inhibit ras-induced oncogenic transformation." (PMID 16640784, 2006). "The IHC results demonstrated that CAF signature genes COL1A2, MFSD5, NOTCH3, and PRSS3 were highly expressed in tumor tissues." (PMID 40781483, 2025). "We found that the EDEM3 expression in epithelial cells (marked by KRT18, EPCAM, KRT8) was significantly higher in tumour tissues with a large proportion of CAFs (marked by COL1A1, COL1A2, COL6A1, COL6A2) in the GSE188711 CRC dataset." (PMID 39754316, 2025). "Between ARGs_Low tumour cells and T cells, ITGB1-CD46 and ITGB1-ENG were ligand-receptor pairs with strong regulatory potential, while COL1A2, CCL3, SERPINE1, FN1 and CDKN1A were top genes target to TGFB1." (PMID 40830065, 2025). "In CRC, the COL11A1 gene is excessively expressed and contributes to tumor advancement by upregulating other genes like THBS2, COL10A1, COL5A2, and COL1A2, thereby driving neoplasia." (PMID 40109582, 2025). "Immunohistochemical analysis revealed elevated H scores for CDK1, STAT1, COL1A2, and COL1A1 in tumor tissues." (PMID 39911265, 2025). "Meanwhile, Domain 4 expressed tumor-suppressive genes like DCN, LUM, BGN, and COL1A2, suggesting a protective microenvironment." (PMID 40838787, 2025). "To elucidate the cellular crosstalk underpinning the COL1A2–ECM–FAK signaling axis identified in bulk RNA-seq, we applied CellChat to dissect intercellular communication networks within the tumor microenvironment." (PMID 41561769, 2025). "MMP2, COL6A3, PRRX1, COL1A2, GREM1 and SNAI2 are integral to the EMT process, a key driver of metastasis that allows tumor cells to detach and invade distant tissues." (PMID 39920655, 2025). "Cancer-associated fibroblasts are important contributors to the EMT featured in the tumor microenvironment, and the EMT phenomenon and the level of COL1A1 and COL1A2 were closely correlated." (PMID 40124621, 2025). "Further examination of the DEPs revealed that several signaling molecules previously identified at the tumor boundary, including ITGB4, COL1A2, and VIM, were significantly upregulated in the cancer-adjacent tissue (p.adjust < 0.05)." (PMID 40725477, 2025). "The significant up-regulation of COL1A2, COL1A1 and DCN in the TME of CC illustrates the phenomenon of fibroblasts’ activation in the tumor microenvironment." (PMID 40124621, 2025). "UMAP analysis of the snATAC-seq data revealed 4 tumor cell clusters with distinct open chromatin patterns in AR (ARPC) and COL1A2 (SARC)." (PMID 40493417, 2025). "Collectively, these findings position COL1A2 as a promising biomarker for monitoring the progression from NMIBC to MIBC and for predicting invasive tumor behavior." (PMID 41561769, 2025).
tumor (continued). "For example, in COL1A1, COL1A2, COL3A1 and COL5A1 HYP peptides were enriched in the tumor nodule boundaries, a pattern that was lost in P4HA2-depleted tumors." (PMID 40671813, 2025). "Our findings highlight the importance of transcriptional co-regulatory mechanisms and ECM remodeling in tumor progression, as well as the potential predictive consequences of ARRB1, COL1A2, MED10, RSP3A and others." (PMID 40362431, 2025). "In contrast, eight genes (COL1A1, COL5A1, COL1A2, COL3A1, WNT2, C1QTNF3, ADAMTS2, GXYLT2) exhibited elevated expression in tumor compared to normal tissue." (PMID 39062832, 2024). "Recent spatial proteomics analysis showed that COL1A2 and COL3A1 were more abundant in the region where the brain and tumour interface." (PMID 39350478, 2024). "Cluster 8 ECs (COL1A1, COL1A2, COL3A1, PDGFRB, and ACTA2) showed an endothelium-mesenchymal transformation phenotype, contributing to tumor progression and metastasis." (PMID 37533434, 2023). "We found that VIM-CD44, COL1A1-CD44, B2M-CD3D, and the interaction between the ligand COL1A1/COL1A2/COL3A1 and the ITGB1 receptor showed significant benefits in the tumor microenvironment of both patients." (PMID 36460803, 2023). "COL1A2 was positively correlated with CD274, CTLA-4, and PDCD1 based on TIMER data which was adjusted by tumor purity." (PMID 37805556, 2023). "LINC00638 exhibited a significant positive correlation with COL1A2 expression in COAD, and the expression levels of LINC00638 in tumor and normal samples was remarkably different." (PMID 37805556, 2023). "COL1A2, COL1A1, COL6A3, and SDC1 were expressed at higher levels in tumor tissue compared with normal tissue in the TCGA-BC, TCGA-CRC, and TCGA-ESCA datasets." (PMID 38002057, 2023). "The fibrillar collagens COL2A1, COL11A1, and COL11A2 show higher expression in the solid tumour region and other fibrillar collagens, COL1A2 and COL3A1, show higher abundance in the brain/tumour interface region." (PMID 38001067, 2023). "Not only were many collagen genes overexpressed in tumor progression between T1 and T2 stages, but also the mRNA expression of these collagen genes, such as COL1A1, COL1A2, COL3A1, COL5A1, COL5A2, COL6A2, and COL6A3, was highly positively correlated." (PMID 36596829, 2023). "COL1A1, together with COL1A2, forms type I collagen, which is the major component of the extracellular matrix (ECM) in connective tissues and COL1A1 displayed tumor-promoting effects in various cancer cells." (PMID 37313172, 2023). "In particular, we noticed that COL1A2, LAMB3, LOX, LTBP2 and S100A6 were significantly upregulated in tumor specimens, when compared with normal tissue." (PMID 35340765, 2022). "Freshly isolated cells were additionally characterized for specific mRNA expression of tumor (GPC3, SPINK1, SPP1, KPNA2) and fibroblast (COL1A2, TWIST2, FGF7) marker genes using RT–qPCR." (PMID 36077764, 2022). "Further, analysis of the association between those ECM components and GC clinicopathological features revealed that increased expression of COL1A2, LOX and LTBP2 significantly correlated with high tumor stage." (PMID 35340765, 2022). "TAMs and CAFs were classified according to their tumor origin and high expression of SPP1, C1QB, IL1B, S100A8, S100A9 and type I collagens (COL1A1 and COL1A2)." (PMID 36209225, 2022). "Tentative identification of the discriminative molecular features showed that collagen fragments (COL1A1, COL1A2, and COL3A1) play a fundamental role in tumor development." (PMID 35956764, 2022). "The expression levels of the known IGC markers MUC13 and CDH1718 and the known DGC markers COL1A2 and SPARC19 increased from GMCs to tumor cells in the tree." (PMID 35087207, 2022). "ITGA2 interacted with COL1A1, COL1A2, COL8A1, FN1, and HSPG2, mediating the tumor cell–fibroblast and tumor cell–endothelial cell connection." (PMID 35719923, 2022).